GLP1R (glucagon like peptide 1 receptor)
Diseases named in the same sentence as GLP1R in open-access papers (continued):
Sharing a sentence is not in itself a finding about the gene and the disease.
prostate carcinoma (continued). "Furthermore, the combined treatment with Ex–4 and metformin significantly increased GLP-1R expression in prostate cancer in vivo." (PMID 26439622, 2015). "Interestingly, the number of prostate cancer cells expressing GLP-1R increased after Ex–4 and/or metformin treatment." (PMID 26439622, 2015). "Additionally, GLP-1R activation inhibits glioma cell migration, invasion, and epithelial-to-mesenchymal transition, as well as suppresses the growth and promotes apoptosis in ovarian and prostate cancer cells." (PMID 39777709, 2025). "Moreover, samples of human prostate cancer tissue and cell lines show an expression of GLP-1R, which may help decrease prostate cancer growth by inhibiting the activation of the ERK-MAPK signaling pathway." (PMID 40282969, 2025). "GLP-1R is overexpressed in certain benign and malignant endocrine tumors, but is generally absent in carcinomas, except for low levels in ovarian and prostate carcinomas." (PMID 40282969, 2025). "Medications, specifically exogenous insulin, statins, and in the future, glucagon-like peptide 1 receptor agonists and sodium–glucose cotransporter 2 inhibitors, may modify the relationship between T2DM, glycemic control, and prostate cancer." (PMID 40693585, 2025). "Studies have shown that GLP-1R expression exists in human prostate cancer and that GLP-1RA can effectively inhibit the growth of prostate cancer, so activation of GLP-1R may be a potential way to treat prostate cancer." (PMID 39465848, 2024). "GLP-1R is widely expressed by various types of cells and tissues in the human body, so GLP-1RA has attracted wide clinical attention to the occurrence, development and prognosis of tumors, which brings more new directions and hopes for the treatment of prostate cancer." (PMID 39465848, 2024). "Such antiproliferative effect of exendin-4 on prostate cancer was not via androgen receptor, but through the inhibition of extracellular signal–regulated kinase-mitogen-activated protein kinase (ERK-MAPK) phosphorylation via GLP-1R." (PMID 27661113, 2017).
liver fibrosis (21 papers, 2015 to 2026). "Previous metabolomic and transcriptomic study of Cotadutide (GLP-1R/GCGR dual agonist) in hepatic fibrosis identified its effects on pathways related to lipogenesis, fibrosis, and inflammation." (PMID 40230860, 2025). "Dwinata and Gracen found that patients using sodium-glucose co-transporter 2 inhibitors (SGLT2i) or glucagon-like peptide-1 receptor agonists (GLP1Ra) have less incidences of diagnosed liver fibrosis." (PMID 38137829, 2023). "That study also demonstrated that a GLP-1R/GCGR dual agonist induced body weight loss across species, which is promising for ALT-801 development to treat NASH and the accompanying liver fibrosis." (PMID 35461369, 2022). "Glucagon-like peptide-1 receptor agonists (GLP-1RAs) have demonstrated efficacy in improving NAFLD, while their effectiveness on liver fibrosis is limited in type 2 diabetic patients." (PMID 36034438, 2022).
psoriasis (21 papers, 2016 to 2026). An autoimmune condition characterized by red, well-delineated plaques with silvery scales that are usually on the extensor surfaces and scalp. "In contrast, agents used in treating T2DM such as biguanides, thiazolidinediones, and glucagon-like peptide-1 receptor (GLP-1) agonists have been noted to be advantageous in combating psoriasis lesions as well." (PMID 34976467, 2021). "Actually, GLP-1 receptor (GLP-1R) mRNA transcripts were detected in the lymphocytes from nonobese diabetic (NOD) mice, in the invariant natural killer T cells (iNKT) from the psoriasis patients, and in the macrophages from normal mice." (PMID 30800001, 2019).
Anorexia (20 papers, 2017 to 2026). Lack of desire to eat (loss of appetite). "By contrast, GLP-1R–expressing neurons in the DVC appear to be a critical site of action for GLP-1RA–induced anorexia and weight loss." (PMID 41542773, 2026). "In the NTS, the emetic chemotherapeutic cisplatin induces cFos activity in GLP-1R neurons, and blockade of these neurons using the GLP-1R antagonist exendin 9-39 attenuates cisplatin-induced anorexia, weight loss and pica in rats [1047]." (PMID 40024571, 2025). "PVN GLP-1R activation caused anorexia and selective blockade of PVN GLP-1R resulted in hyperphagia and weight gain." (PMID 28223965, 2017). "This was done for a GLP-1R agonist, an anti-diabetic drug known to cause anorexia in some patients." (PMID 33903632, 2021). "Activation of GLP-1R on NTS astrocytes results in increased cAMP levels in astrocytes, and pharmacological inhibition of astrocytes prevents GLP-1R/exendin-4-induced anorexia, demonstrating a key role for astrocytes in GLP-1-induced feeding suppression." (PMID 38887265, 2024). "We therefore predicted that inhibition of GLP1R vagal afferents, similar to inhibition of PBeCGRP neurons, would reduce LiCl-induced anorexia." (PMID 34043943, 2021). "Glp-1 signaling has been shown to exert an anorectic effect and blocking of Glp1r signaling using specific antagonists has been shown to blunt stress-induced anorexia." (PMID 32894221, 2020). "Caspase-mediated ablation of ARC GLP-1R–expressing neurons did not block semaglutide-induced weight loss, and CRISPR-mediated GLP-1R knockout in the ARC did not affect acute liraglutide-induced anorexia." (PMID 41542773, 2026). "Direct intra-hypothalamic GLP-1R agonism also induces anorexia." (PMID 39225090, 2024). "While our data support delayed gastric emptying and nausea contributing to the anorexia observed following LC GLP-1R activation, other factors may also be at play." (PMID 37729419, 2023). "NK1R and GLP-1R play an important role in DON-induced anorexia." (PMID 36548782, 2022). "Only GLP1R in the CNS followed a similar tendency with LeptinR and INSR, suggesting that GLP1 induced anorexia possibly directed central pathways." (PMID 32355579, 2020). "Optogenetic stimulation of GLP-1R–expressing TRH-positive neurons in the ARC also suppressed feeding via AgRP neuron inhibition, and AgRP neuron stimulation partially overcame Ex-4 or TRH-neuron stimulation–induced anorexia." (PMID 41542773, 2026). "Moreover, chemogenetic inhibition of PVH GLP-1R neurons enhanced food intake, but did not attenuate acute liraglutide-induced anorexia." (PMID 41542773, 2026). "However, when coadministered with GLP-140, GIP-085 was able to reduce kaolin consumption driven by GLP-1R activation and it also significantly attenuated GLP-140–induced anorexia at 72 hours, resulting in a 7- ± 6-g significant attenuation of GLP-140–induced body weight loss." (PMID 40532005, 2025).
Glucose intolerance (20 papers, 2010 to 2024). Glucose intolerance (GI) can be defined as dysglycemia that comprises both prediabetes and diabetes. "Thus, blockade of hepatic portal GLP-1R signaling causes glucose intolerance in rats, suggesting that GLP-1Rs located on nerve terminals in the hepatic portal vein contribute to the incretin action of GLP-1." (PMID 25852463, 2015). "We here assessed whether typical pathogens of laboratory mice affect the development of diet-induced obesity and glucose intolerance, and whether colonization affects the efficacy of the GLP-1R agonist liraglutide and of the GLP-1/GIP co-agonist MAR709 to treat obesity and diabetes." (PMID 39019114, 2024). "For example, lean chow-fed Glp1r βcell–/–:Gcgrβcell–/– mice exhibit normal oral and IP glucose tolerance as compared to wild-type controls; however, metabolically stressed Glp1rβcell–/–:Gcgrβcell–/– mice exhibit impaired oral and IP glucose intolerance as compared to HFD-fed controls." (PMID 35957816, 2022). "Thus, GLP-1R agonists may offer advantages for patients suffering from steroid diabetes or glucose intolerance as a side effect of long-term GC therapy." (PMID 24423471, 2014). "As glucose intolerance and insulin resistance have been linked to ALS, and in light of the neurotrophic and protective actions of GLP-1R activation in diverse cellular and animal models of neurodegeneration, we hypothesize that GLP-1 and analogues may provide neuroprotective actions in ALS." (PMID 22384126, 2012). "A subset of α cells in culture showed GLP-1R expression and α-cell specific GLP-1R knockout (KO) mice exhibit mild glucose intolerance and increased glucagon secretion in response to glucose challenging compared with wild-type animals, suggesting a possible direct effect of GLP-1 on this cell." (PMID 37729025, 2023). "GLP-1R agonists are a class of drugs targeting the incretin system that are now being investigated as potential medications to treat GDM, due to numerous recent publications showing their beneficial effects on insulin sensitivity and glucose intolerance during pregnancy." (PMID 37590249, 2023). "Administration of the GLP-1R agonist liraglutide before the onset of WS symptoms offers great protection against disease progression by postponing the development of glucose intolerance (as opposed to late intervention) and protecting against vision loss current paper in an animal model of WS." (PMID 34831417, 2021).
prediabetes (20 papers, 2014 to 2026). "Early data also support a role for glucagon-like peptide-1 receptor agonists (GLP-1RAs) in delaying the conversion from prediabetes to T2DM." (PMID 24524730, 2014).
inflammatory bowel disease (19 papers, 2013 to 2026). A spectrum of small and large bowel inflammatory diseases of unknown etiology. "Glucagon like-peptide 1 receptor (GLP-1R) agonists diminish appetite and may contribute to the weight loss in inflammatory bowel disease (IBD)." (PMID 29813107, 2018). "Glucagon-like peptide-1 receptor agonists are increasingly recognized for their potential dual benefit in inflammatory bowel disease (IBD), offering metabolic advantages alongside emerging anti-inflammatory, immunomodulatory, and gut barrier-enhancing effects." (PMID 40972535, 2025). "Interestingly, in colonic mucosal biopsies from individuals with inflammatory bowel disease, these genes were upregulated in inflamed tissue compared with noninflamed mucosa from the same patients, while GLP1R expression was downregulated." (PMID 41178710, 2025).
ischemia (19 papers, 2011 to 2026). A hypoperfusion of the BLOOD through an organ or tissue caused by a PATHOLOGIC CONSTRICTION or obstruction of its BLOOD VESSELS, or an absence of BLOOD CIRCULATION. "In acute experiments, GLP-1 agonists reduced damage to the heart from ischemia in wild-type mice compared to mice with knock out of GLP-1R." (PMID 39339176, 2024). "Its protective mechanism and analogs in myocardial cells with ischemia injury are now better-understood thanks to this report, which is the first to image GLP-1R in myocardial cells that have undergone MI/R." (PMID 37780209, 2023). "GLP-1R agonist has a protective effect on ischemia by reducing inflammatory factors and BBB breakdown in an astrocyte-dependent manner." (PMID 31779652, 2019). "Myocardial increment of GLP-1R during acute ischemia was similar to that seen in the renal tubule; however, changes in progenitor cells were different." (PMID 30823876, 2019). "The GLP-1 analog, exendin-4, protects against ischemia-induced neuronal apoptosis by inducing GLP-1R expression in a model for transient cerebral ischemia." (PMID 29156769, 2017). "First, we evaluated the GLP-1R dependent effects of Ex-4 in experiments that investigated ischemia/reperfusion injury." (PMID 25194961, 2014). "Moreover, GLP-1R agonists have been shown to abate microglial activation in vivo in WS rats and increase GABAergic neurotransmission in different disease conditions, including ischemia." (PMID 37107585, 2023). "Similarly, myocardial GLP-1R is also increased in early ischemia and decreased in later disease." (PMID 30823876, 2019). "We also demonstrated that efficiently blocking C3d+ A1 astrocyte conversion using semaglutide, a glucagon-like peptide-1 receptor (GLP-1R) agonist, reduces ischemia-induced BBB disruption and improves neurobehavioral recovery." (PMID 35656116, 2022). "In our recent study, we reported that stimulation of GLP-1R enhanced APE1 expression and BER activity; moreover, administration of Exendin-4 (EX-4), a GLP-1R agonist, substantially reduced ischemia-induced nuclear DNA damage in brain cells." (PMID 28846606, 2017). "Exendin-4, an exogenous glucagon-like peptide-1 receptor (GLP-1R) agonist, protects the heart from ischemia/reperfusion injury." (PMID 25194961, 2014).
osteoporosis (18 papers, 2018 to 2026). A condition of reduced bone mass, with decreased cortical thickness and a decrease in the number and size of the trabeculae of cancellous bone (but normal chemical composition), resulting in increased fracture incidence. "We employed three genetic models to assess the association between GLP-1R genetic variants and osteoporosis in postmenopausal women, while also investigating SNP-SNP and SNP-environment interactions with the risk of PMOP." (PMID 38096145, 2023). "Thus, more large-scale human prospective studies are needed to evaluate the efficacy of Glp1r agonist or DPP-4 inhibitor in treating diabetic-associated osteoporosis." (PMID 35581617, 2022). "Due to the great impact of inflammation and stress on the occurrence of osteoporosis, we further investigated whether miR-27a-3p-targeting-GLP1R is implicated in inflammatory response." (PMID 35069685, 2021). "Current studies reported that GLP1R is associated with the occurrence of osteoporosis." (PMID 35069685, 2021). "Therefore, we assumed that miR-27a-3p/GLP1R might be implicated in osteoporosis via influencing osteoclast behaviors and plan to evaluate such axis in osteoclasts." (PMID 35069685, 2021). "Since osteoblasts and osteoclasts work in tandem to maintain bone homeostasis and disruptions can lead to osteoporosis, the GLP1R gene emerges as a strong candidate for FLBW due to its influence on bone growth." (PMID 38200769, 2023). "An early study has reported that overexpressing GLP1R dramatically increases bone mass, improves bone microstructure, and enhances the anti-osteoporosis ability of organisms." (PMID 35069685, 2021). "In this mechanism, downregulation of GLP1R by miR-27a-3p inhibited AMPK phosphorylation to suppress osteoblast autophagy and differentiation, thus causing osteoporosis." (PMID 35069685, 2021). "Further, we validated that the regulatory relationship between GLP1R and miR-27a-3p influenced osteoporosis." (PMID 35069685, 2021). "The research on the regulation of miR-27a-3p-GLP1R is helpful to our understanding of the molecular mechanism of osteoporosis, thus contributing to finding the therapeutic target underlying this disease." (PMID 35069685, 2021). "GLP-1R agonists also had protective effects in animal models of osteoporosis." (PMID 39858999, 2024). "At present, there are few clinical studies about the effects of GLP-1R agonists on osteoporosis." (PMID 39858999, 2024). "Hence, this work investigated the molecular mechanism of miR-27a-3p targeting GLP1R and the effect of the regulatory relationship between these two genes on osteoporosis differentiation." (PMID 35069685, 2021). "After verifying the regulatory relationship between miR-27a-3p and GLP1R, subsequent cellular function assay showed that miR-27a-3p inhibited GLP1R expression to affect osteoblast autophagy and differentiation, which played a vital role in osteoporosis." (PMID 35069685, 2021). "We, therefore, speculated that miR-27a-3p targeted GLP1R to affect the occurrence of osteoporosis." (PMID 35069685, 2021). "The interplay between miR-27a-3p and GLP1R may be a vital factor in the occurrence of osteoporosis." (PMID 35069685, 2021). "Thus, although GLP-1R/GIPR agonists may result in significant weight loss, the co-administration of dual GLP-1R/GIPR agonists could potentially shield patients from concurrent osteoporosis by exploiting the inherent antiresorptive properties of GIP and GLP-1." (PMID 38725663, 2024). "In sum, we found that GLP1R regulated the activity and autophagy of the AMPK signaling pathway to influence the occurrence of osteoporosis." (PMID 35069685, 2021). "GLP1R is a G protein-coupled receptor of GLP-1 that activates GLP1R to regulate the insulin secretion, thus affecting osteoporosis." (PMID 35069685, 2021).
ischemic stroke (17 papers, 2016 to 2026). A stroke disorder caused by obstruction of blood flow to the brain, due to thrombotic (local blood clot formation) or embolic (due to a blood clot or other material traveling from another site) event. "Concluding a null effect of GLP1R agonism would directly contradict meta-analyses of clinical trials that have shown a beneficial effect of GLP1R agonists on ischemic stroke risk." (PMID 39628323, 2024). "Therefore, our results indicate that the GLP-1R agonist may be a potential therapeutic agent to decrease the risk of rtPA-induced HT after ischemic stroke via the Wnt/β-catenin signaling pathway." (PMID 35359227, 2022). "With regard to the potential impact of GLP-1RA on hemorrhagic stroke, pre-clinical studies showed the potential role of GLP-1/GLP-1R axis in reducing hemorrhagic transformation after ischemic stroke." (PMID 36829226, 2023). "In conclusion, this study shows that GLP-1R activation mediates neuroprotection against ischaemic stroke established by remote ischaemic conditioning." (PMID 33942194, 2021). "The results of the present study suggest that RIC-induced neuroprotection against ischaemic stroke is mediated by a similar mechanism involving GLP-1R-mediated signalling." (PMID 33942194, 2021). "Recent research has showed neuroprotective properties against ischemic stroke by drugs targeting GLP-1R." (PMID 26863436, 2016). "Studies on experimental models of ischemic stroke and subarachnoid hemorrhage indicate that GLP-1R agonists and analogs can promote the phosphorylation of PI3K and AKT, inhibit inflammatory responses, and thereby provide neuroprotective and vasculoprotective effects." (PMID 40224490, 2025). "Furthermore, in the context of primary prevention, the improvement in glycemic control after treatment with the glucagon-like peptide-1 receptor agonists (GLP-1RA) semaglutide and dulaglutide was associated with a reduction in the risk of ischemic stroke in diabetic subjects." (PMID 39407846, 2024). "Moreover, stimulation of GLP-1R may widen cerebral arteries, increase blood flow, reduce infarct volume, and ameliorate neurological deficit symptoms produced by ischemic stroke, which implies that GLP-1R agonists have neurotrophic and neuroprotective effects in nervous system disease." (PMID 40224490, 2025). "Plenty of evidence indicated that iridoid glycosides, as small molecule non-peptide GLP-1R agonists, were an optional treatment strategy against ischemic stroke." (PMID 34867417, 2021). "We investigated the effects of treatment with either glucagon-like peptide-1 receptor agonists (GLP-1RA) or sodium-glucose contrasporter-2 inhibitors (SGLT-2i) on endothelial glycocalyx, arterial stiffness, and LV myocardial strain in patients with metformin-treated T2DM and a prior ischemic stroke." (PMID 41752654, 2026). "First, we determined the effect of GLP-1R blockade on RIC-induced neuroprotection, and then investigated the expression of GLP-1R and the effects of GLP-1R activation on cerebral blood vessels and brain blood flow, as a potential mechanism of GLP-1R-mediated neuroprotection against ischaemic stroke." (PMID 33942194, 2021).